EZR (ezrin)
Diseases named in the same sentence as EZR in open-access papers (continued):
Sharing a sentence is not in itself a finding about the gene and the disease.
tumor (continued). "Cytoskeletal proteins like STMN1 and EZR not only regulate essential cellular processes but also contribute to tumor progression, underscoring the value of targeting them for novel therapeutic approaches." (PMID 40982350, 2025). "EMT can downregulate the enrichment of ezrin in lamellipodia and reduce the formation of lamellipodia in tumor cells, thereby transforming tumor epithelial cells into a mesenchymal migratory phenotype and facilitating tumor metastasis." (PMID 39799341, 2025). "Studies have highlighted its role in important cellular processes and the correlation between high levels of EZR expression and tumor progression and metastasis, as well as worse prognosis." (PMID 38972247, 2024). "Crucially, Ezrin emerges as a potent regulator of tumor cell invasion and metastasis, emphasizing its multifaceted significance in cancer biology." (PMID 38900156, 2024). "Ezrin-mediated cell polarity plays an essential role in tumor cell adhesion and the ability of tumor cells to move across the endothelium." (PMID 39791707, 2024). "In the realm of traditional Chinese medicine, the active component baicalin downregulates Ezrin in PCa cells and mice, restraining cell proliferation, inducing apoptosis, arresting the cell cycle, and reducing tumor dimensions." (PMID 39055653, 2024). "Circulating tumor cells (CTCs) expressing the dynamic polarity of the cytoskeletal membrane protein, ezrin, have been proposed to play a crucial role in tumor progression and metastasis." (PMID 39791707, 2024). "An impairment in ezrin phosphorylation at tyrosine 478 reduces the formation of actin-rich protrusions in epithelial cancer cells and tumor-induced endothelial branching." (PMID 39158743, 2024). "It is possible that the induced migration observed here is due to a well‐documented increase in K7M2 ezrin protein expression, which has known correlations with hypoxia‐induced cell motility and tumor invasion in other cancers." (PMID 39300969, 2024). "Ezrin’s expression in circulating tumor cells is likely related to the level of circulating Ezrin in the blood flow." (PMID 37371090, 2023). "A recent study reported that the interaction of ICAM-1 and Ezrin destructs the endothelial barrier and enhances vascular permeability, therefore promoting tumor metastasis." (PMID 37371090, 2023). "In this study, we have shown that PDAC cell‐derived sEVs with ezrin activate normal fibroblasts, and reciprocally, activated fibroblasts promote tumor invasion and proliferation in in vitro transwell assays and co‐culture experiments." (PMID 37171030, 2023). "This process has been linked to the metastatic behavior of tumors, where adhesion molecules, through Ezrin-mediated linkages to actin, confer to tumor cells the capacity to migrate within tissues, through vessels, and attach to metastatic organs." (PMID 37371090, 2023). "Ezrin plays a critical role in regulating tumor metastasis through interaction with other binding proteins." (PMID 37371090, 2023). "Mutations of ARID2, CUL3, TET1, FBXW7, EZR and GPHN were frequently accompanied by copy number loss consistent with their predicted/documented tumour suppressor roles." (PMID 38106039, 2023). "Another way Ezrin aids tumor cells in evading the immune system is through its interaction with programmed cell death ligand-1 (PD-L1)." (PMID 37371090, 2023). "CD44 has been shown to promote tumor growth and invasiveness by recruiting Ezrin to its cytoplasmic tail and thus producing links to the cytoskeleton." (PMID 37371090, 2023). "Ezrin was mainly expressed by circulating tumor cells in contrast to leukocytes, which expressed other actin-binding proteins." (PMID 37371090, 2023). "β-catenin is known to mediate tumor metastasis through interactions with Ezrin and the NF-κB pathway." (PMID 37371090, 2023). "Ezrin protein expression was associated with worse NPI prognostic group, whereas ezrin mRNA expression was associated with ER‐positive tumours and PAM50 subtype." (PMID 36938826, 2023).
tumor (continued). "Ezrin interacts with E-cadherin to regulate cell–cell and cell–matrix adhesion, therefore controlling tumor cell adhesion and invasiveness." (PMID 37371090, 2023). "Ezrin, which is thought to play an active role in regulating tumor growth and progression or dissemination of many cancers, was found to have strong intensity in nine cases." (PMID 37999140, 2023). "Ezrin binds with many different metastasis-related proteins and induces a variety of reactions in tumor metastasis." (PMID 37371090, 2023). "In contrast, suppression of Ezrin phosphorylation attenuates NK cell internalization into tumor cells." (PMID 37371090, 2023). "Like Ezrin and Moesin, Radixin is overexpressed in many tumor tissues and can modulate the viral infection process for several viruses by regulating stable microtubule function." (PMID 37371090, 2023). "Our findings revealed that the highest level of ezrin protein expression was found in cancer tissue and that this level gradually decreased as we moved away from the tumor indicating its potential role in the development or progression of BC." (PMID 37061568, 2023). "Osteopontin is reported to be an integral part of this hyaluronan–CD44–Ezrin complex, where the malignant secretion of osteopontin and CD44 variant isoforms has caused the migration of tumor cells to specific sites of metastasis formation." (PMID 37371090, 2023). "By interacting with ezrin/radixin/moesin, S100P can promote trans-endothelial migration of tumor cells, thereby favoring metastasis." (PMID 37627239, 2023). "Here, we review the main functions of Ezrin, the mechanisms through which it acts, its role in tumor metastasis, and its potential as a therapeutic target." (PMID 37371090, 2023). "Ezrin protein is found in almost all human tissue cells and involved in the regulation of tumor cell adhesion, motility, signal transduction, and metastasis." (PMID 37791063, 2023). "Alongside regulating the expression of angiogenic factors in macrophages, Ezrin can also regulate their expression in tumor cells." (PMID 37371090, 2023). "Localized within phagocytic vacuoles, the downregulation of Ezrin leads to the decreased phagocytic activity of metastatic tumor cells." (PMID 37371090, 2023). "Tumor cells in the bloodstream exert cortical ezrin-rich poles to adhere to vascular endothelium and subsequently facilitate the metastases processes." (PMID 36499486, 2022). "Congruent with this study, we also found a significant correlation between Ezrin expression and Breslow tumor thickness (p = 0.018)." (PMID 36142656, 2022). "Pancreatic cancer cells secrete Ezrin-rich EVs into the tumor microenvironment, which in turn polarizes macrophages that promote tumor metastasis." (PMID 35501802, 2022). "ICAM-3 is an adhesion molecule that can interact with LFA-1 extracellularly or ezrin/radixin/moesin intracellularly, contributing to tumor metastasis." (PMID 36059515, 2022). "The severe impairment of CSC frequency, self-renewal capacity, and tumor initiation potential was observed following the knockout or inhibition of ezrin." (PMID 36355541, 2022). "Vimentin and ezrin show clinical significance in samples obtained from OS patients but need circulating tumor cell purification, since they are expressed in leukocytes." (PMID 35625426, 2022). "Recent studies show that Ezrin can act as a tumor metastasis regulator in invasion and metastasis of many types of cancer." (PMID 35311087, 2022). "Previous studies have proven that circulating tumor cells (CTCs) and Ezrin are involved in PCa progression, metastasis, diagnosis, and prognosis." (PMID 35156523, 2022). "We previously reported higher ezrin mRNA and protein in tumor compared with benign tissue, consistent with the cell lines data shown here." (PMID 36923551, 2022). "MiR-96, miR144, miR-150, miR-183, and miR-211 inhibit cell proliferation, invasion, migration, and tumor formation by targeting ezrin." (PMID 36077137, 2022).
tumor (continued). "We found a significant correlation between Breslow tumor thickness and Ezrin expression (p = 0.018)." (PMID 36142656, 2022). "The combination of PARP inhibitor with ezrin phosphorylation inhibitor effectively reduced both tumor growth and lung metastasis in OS mouse models." (PMID 35173550, 2022). "Previous studies have shown that Ezrin can participate in cell processes in health and disease relate to development, and metastasis of tumours, and cell adhesion, movement and angiogenesis through a variety of signalling pathways." (PMID 34459110, 2021). "Enriched exosomal Ezrin protein can regulate M2 macrophage polarity which consequently leads to tumour metastasis." (PMID 34671031, 2021). "Considering the crucial role of the AKT pathway in tumor progression, we examined the effect of circCDYL2 on Ezrin expression and AKT phosphorylation by Western blotting." (PMID 34485151, 2021). "Injection of patient-derived exosomes that expressed Ezrin before and post tumour injection into mouse models facilitated tumour metastasis to liver." (PMID 34671031, 2021). "Multiple studies have demonstrated that Ezrin overexpression in tumor cells increases their metastatic potential." (PMID 34485151, 2021). "DNAH5, LTF, and Ezrin were significantly increased in tumor tissues (p < 0.05), and WNT7A displayed a slight increase (p = 0.0669)." (PMID 35178403, 2021). "In these samples, the localization of ezrin in the primary tumor was in the cell membrane, and changed to the cytoplasm in passage X2, suggesting an enrichment of more aggressive cancer cells." (PMID 34198671, 2021). "A meta-analysis of ezrin function showed that ezrin participates in tumor metastasis and invasion, and tumorigenesis by manipulating cellular activities (e.g., adhesion, motility and proliferation)." (PMID 34063807, 2021). "Studies have confirmed that EZR is overexpressed in many human cancers and involved in many aspects of tumor cell migration." (PMID 34429402, 2021). "SIX1 activates the transcription of potent oncogenes and stem cell regulators, such as c-MYC and ezrin, that have a vital role in tumor invasion and signal transduction in many cancers." (PMID 34771571, 2021). "We further determined the role of ezrin in macrophage polarization, and communication between macrophages and tumor cells." (PMID 33086476, 2020). "Our results indicate that macrophage ezrin contributes to tumor microenvironment-directed polarization." (PMID 33086476, 2020). "By stimulating the epithelial-to-mesenchymal transition, ezrin is thought to promote tumor metastasis in breast and osteosarcoma cancer cells." (PMID 33086476, 2020). "In primary melanomas of the skin and metastatic tumors, Ezrin expression correlates with tumor progression and suggests worsening clinical disease behaviors." (PMID 33240887, 2020). "Tenascin-C (TNC) has been demonstrated to have an angiogenic role in GBM; ezrin to inhibit NF2 tumor-suppressor in GBM." (PMID 33374813, 2020). "Macrophages profoundly influence tumorigenesis, and here we explore ezrin’s influence on tumor-promoting macrophage functions." (PMID 33086476, 2020). "Surprisingly, patients with positive Ezrin expression had smaller tumor sizes and a higher frequency of tumor dedifferentiation and vascular invasion." (PMID 33240887, 2020). "The level of ezrin expression and its activation state, as well as the subcellular localization of ezrin, are important factors in tumor progression." (PMID 31936668, 2020). "Positive expression of ezrin in gastric cancer correlated with age, tumor size, location, and depth of invasion." (PMID 33171868, 2020).
tumor (continued). "Our understanding of Ezrin as a potential drug target is strongly influenced by the idea that Ezrin is commonly proved to promote tumor metastasis and predicts poor prognosis in different types of cancers." (PMID 33240887, 2020). "Ezrin plays a critical role in extracellular matrix remodeling and tumor dissemination in a 3-dimensional model." (PMID 33240887, 2020). "There was a statistically significant relation between ezrin IHC expression and tumor grade (P- value = 0.046)." (PMID 32334457, 2020). "In HCC tissues, high levels of ezrin expression associated with advanced Tumor, Nodes, Metastases (TNM) stage, poor Edmondson’s histological grade, macroscopic portal vein invasion, tumor recurrence and extrahepatic recurrence." (PMID 31991677, 2020). "Subsequently, we investigated the role of macrophage ezrin in the tumor cell-mediated reprogramming of polarization." (PMID 33086476, 2020). "There was a statistically significant relation between ezrin expression and tumor grade (p-value <0.05)." (PMID 32334457, 2020). "Ezrin as an essential prognosis predictor of various cancers has been demonstrated to be a key modulator of tumor metastasis." (PMID 33240887, 2020). "In this review, we focus on Ezrin’s distinct roles in tumor growth, metastasis, and morphogenesis in cancer biology, because increased Ezrin expression is correlated with poor prognoses in various cancers." (PMID 33240887, 2020). "Our results suggest that macrophage ezrin contributes to the polarization to a more M2-like subtype that can contribute to pro-tumorigenic activity in the tumor microenvironment." (PMID 33086476, 2020). "Tumor cell ezrin expression and function have been investigated in depth; however, its role in macrophages and other tumor microenvironment cells remains unexplored." (PMID 33086476, 2020). "We have shown here for the first time that the EZRIN protein, which has been previously shown to be a key regulator of tumor metastasis, is a crucial mediator of SNAIL signaling pathways by acting as an actin filament-plasma membrane linker." (PMID 32664538, 2020). "As a surrogate for the investigation of monocyte homing to tumor-initiating sites, we determined the influence of myeloid cell ezrin on endothelial cell adhesion and the cancer cell-directed migration of THP-1 cells." (PMID 33086476, 2020). "Ezrin expression is correlated with tumor size, tumor location, lymph node invasion and metastasis, and shortened survival in stages I, II, and III." (PMID 33240887, 2020). "Ezrin was expressed in 92.2% of cases, and it showed a statistical significant relation with tumor grade." (PMID 32334457, 2020). "We investigated the role of ezrin in the tumor cell-directed education of macrophages regarding the angiogenic factor production." (PMID 33086476, 2020). "Here we provide evidence that CHL1 firmly interacts with ezrin in NB cells, and that this interaction leads to a higher neuronal differentiation degree and, consequently, to a lower tumor invasiveness potential." (PMID 33326488, 2020). "Ezrin is mostly known as a molecule correlated with tumor progression, able to provoke EMT transition and metastases, also when it interacts with L1 cell adhesion molecules." (PMID 33326488, 2020). "These experiments suggest that macrophage ezrin is a key factor in cell responses to cues in the tumor microenvironment that determines the macrophage secretion of pro-angiogenic factors that contribute to vessel growth and tumorigenesis." (PMID 33086476, 2020). "Firstly, Iru has a higher affinity than Ori towards Ezrin, and this determines its effectiveness in inhibiting the invasion capacity of tumor cells." (PMID 33003361, 2020). "High expression of the Ezrin gene in circulating tumor cells was also found to correlate with distant metastases." (PMID 30754703, 2019).
tumor (continued). "This abnormal localization changes the interacting proteins of ezrin, which has been shown to be critical for regulating tumor cell survival, invasion, and metastasis." (PMID 31886273, 2019). "We then extended our study to an in vivo xenograft model and demonstrated that Ezrin knockdown significantly reduced tumour growth and incidence of lung metastasis." (PMID 30804430, 2019). "Knockdown of ezrin in an MDA-MB-231 orthotopic tumor model also resulted in significant reductions in axillary LN and lung metastases." (PMID 30678714, 2019). "Results manifested that compared with those in para‐carcinoma tissues, Ezrin, LaminA/C, and cleaved caspase‐3 expressions were significantly declined in tumor tissues (P < 0.01), but the Bcl‐2/Bax ratio was increased significantly (P < 0.01)." (PMID 31578772, 2019). "Ezrin was also known as a key molecule connected with many other molecules in the biology of tumor development." (PMID 31886273, 2019). "We have previously shown that tumor ezrin levels correlate with lymphovascular invasion in a locally accrued BC cohort and that ezrin acts cooperatively with Src in regulating tumor lymphangiogenesis." (PMID 30678714, 2019). "Our current study demonstrated that high expression of Ezrin indicated the high tumour invasion and poor prognosis in BC." (PMID 30804430, 2019). "Ezrin inhibition reduced the number of tumor colonies per node and metastatic burden by 50% and 70%, respectively." (PMID 30678714, 2019). "Since EMT is an important component in tumour metastasis and invasion, we next investigate the effect of Ezrin on EMT in BC." (PMID 30804430, 2019). "Several studies have demonstrated that knocking down ezrin and P65 expression induces tumor metastasis in different cancers." (PMID 31827401, 2019). "Together, with elevated ezrin expression in LN metastases compared to matched primary tumors, these data support our contention that ezrin overexpression confers a metastatic advantage to BC cells during tumor progression." (PMID 30678714, 2019). "HGF, among other functions, regulates actin-surface-interactions by the interaction of ezrin and FES kinase, which phosphorylates ezrin at tyrosine 477, resulting in the scattering of tumour cells." (PMID 31382374, 2019). "The limitation in our study still exists that the controversial result regarding the changes in Ezrin, LaminA/C in tumor tissues, and the potential mechanisms remain to be further investigated." (PMID 31578772, 2019). "Analysis of a small subset of matched primary tumor and LN-positive lesions from the same patient revealed significantly higher ezrin expression in LN metastases." (PMID 30678714, 2019). "In vivo, overexpression of ezrin inactivates the tumor suppressor function of merlin in a glioblastoma cell line." (PMID 31018575, 2019). "In all, these results suggested that Ezrin promotes tumour progression at least in part via the AKT pathway." (PMID 30804430, 2019). "Next, we developed a quantitative intravital microscopy (qIVM) approach, using a syngeneic lymphatic reporter mouse tumor model, to investigate the effect of systemic ezrin inhibition on cancer cell migration and metastasis." (PMID 30678714, 2019). "In contrast, the weights of tumours were significantly increased in Ezrin-overexpressed group compared to the control group." (PMID 30804430, 2019). "The weights of tumours that generated from the Ezrin-depleted cells were markedly decreased in comparison with the si-con group." (PMID 30804430, 2019). "The clinicopathological analysis revealed that Ezrin expression was closely correlated with tumour differentiation (P = 0.015), late TNM stage (P = 0.004) and LN metastasis (P = 0.003)." (PMID 30804430, 2019). "Ezrin can promote tumor invasion, and in various malignancies, including uveal melanoma, is significantly associated with outcome of the disease." (PMID 31039200, 2019).